NOS1 (nitric oxide synthase 1)
Diseases named in the same sentence as NOS1 in open-access papers (continued):
Sharing a sentence is not in itself a finding about the gene and the disease.
schizophrenia (continued). "The number of studies suggesting impaired prefrontal functioning in schizophrenia continue to increase and there is increasingly more evidence of the genetic variation of NOS1 in cognitive dysfunction, probably by decreasing glutamatergic transmission." (PMID 32111088, 2020). "We further pinpointed two genes ATP2B2 (rs9879311, P = 2.77 × 10−6) and NOS1 (rs2293052, P = 1.24 × 10−6), which were closely connected to the NMDAR interactome and showed strong associations with schizophrenia risk." (PMID 30323833, 2018). "The authors studied the role of polymorphisms of genes NOS1 and NOS1AP in schizophrenia development." (PMID 26029110, 2015). "As of right now, there are associative investigations of polymorphisms of gene of neuronal NO-synthase carried out in patients with schizophrenia (is coded by NOS1 gene)." (PMID 26029110, 2015). "These include NOS1, AKT1, DTNBP1, DNMT1, PPP3CC and SOX10, which have previously been associated with schizophrenia." (PMID 24399042, 2014). "NOS1 is considered to be a likely candidate gene for schizophrenia owing to its chromosomal location, 12q24, which has been reported to be a susceptibility locus from several linkage studies, and to play a role in producing NO in the human brain." (PMID 21886582, 2011). "Because the symptomatology of methamphetamine (METH) use disorder patients with psychosis is similar to that of patients with schizophrenia, NOS1 is a good candidate gene for METH-induced psychosis." (PMID 21886582, 2011). "For example, malformation of NOS1 positive GABAergic interneurons was described in schizophrenia." (PMID 36233204, 2022). "Also, we recently showed that polygenic risk of schizophrenia variants identified by GWAS is enriched within two redox-related pathways including NOS1 (Nitric Oxide Synthase 1) and HIF-2 (Hypoxia-Inducible Factor-2) signalling." (PMID 33276438, 2020). "NOS1 is a relevant functional and positional candidate gene for schizophrenia." (PMID 33424660, 2020). "The precise nature of the relationship between arginine and oxidative stress in neuropsychiatric disorders is unclear; however, the common susceptibility genes for ASD and schizophrenia, TCF4 and NOS1 has been suggested to be involved in the arginine-NO pathway." (PMID 24058493, 2013). "Other genes involved in the activity of NOS1 may be related to the pathophysiology of psychotic disorders such as schizophrenia and METH-induced psychosis." (PMID 21886582, 2011). "Mice lacking Nos1 gene have been shown deficits in executive function and spatial memory and in humans, NOS1 mutations have been identified as risk factor for schizophrenia, particularly with schizophrenia with profound impairment in cognitive function." (PMID 32211019, 2020). "Thus, their results also do not support the previously identified association between NOS1 gene polymorphisms and schizophrenia." (PMID 32111088, 2020). "Therefore, NOS1 is recognized to be candidate gene for schizophrenia." (PMID 21886582, 2011). "We also found DNMT1, NOS1 and SOX10 to be differentially methylated in brain tissue from patients with schizophrenia." (PMID 24399042, 2014). "However, a previous study did not report an association between NOS1 and schizophrenia." (PMID 21886582, 2011). "Thus, there is increasing evidence that NOS1 and NOS3 are promising drug targets for treating schizophrenia and affective disorders." (PMID 36233204, 2022).
ischemic stroke (31 papers, 2013 to 2026). A stroke disorder caused by obstruction of blood flow to the brain, due to thrombotic (local blood clot formation) or embolic (due to a blood clot or other material traveling from another site) event. "Moreover, a genome-wide association study (GWAS) for ischemic stroke identified NOS1 as a strong candidate gene." (PMID 37240727, 2023). "Although NOS1 rs2293054 has not yet been studied in AD, association with clinical phenotypes of ischemic stroke and Parkinson’s disease treatment was observed." (PMID 36829875, 2023).
Alzheimer disease (29 papers, 2016 to 2025). A progressive, neurodegenerative disease characterized by loss of function and death of nerve cells in several areas of the brain leading to loss of cognitive function such as memory and language. "For miR‐328‐5p, Gys1 (AMPK signaling pathway), Nos1 (Alzheimer's disease) and Pak6 (ErbB signaling pathway) were identified." (PMID 39317458, 2024). "Between RELN and NOS1, three exons are altered in their expressions in the human hippocampus affected by Alzheimer’s disease." (PMID 30704480, 2019). "Altered expression patterns (exon skipping events) within two distinct exon regions of RELN and NOS1 in the human hippocampus affected by Alzheimer’s disease (AD) were identified." (PMID 30704480, 2019). "NOS1 represents the predominant NO-producing enzyme highly enriched in the brain and known to mediate multiple functions, ranging from learning and memory development to maintaining synaptic plasticity and neuronal development, Alzheimer’s disease (AD), psychiatric disorders and behavioral deficits." (PMID 35821897, 2022). "Berberine, an isoquinoline alkaloid, regulates the miR‐188/nitric oxide synthase 1 (NOS1) pathway, promoting cell viability and attenuating Aβ‐induced neuronal damage in Alzheimer's disease." (PMID 40804606, 2025). "CASP9 and PTGS2 in neurodegeneration_multiple diseases, NOS1, NOS2 in Alzheimer disease pathway were identified as core targets." (PMID 37904435, 2023). "The Alzheimer disease pathway is the second-ranked signaling pathway, and 5 key targets, CASP9, APP, NOS2, NOS1 and PTGS2, are enriched in this pathway." (PMID 37904435, 2023). "Ten DEGs, including IGF1, VEGFC, RAPGEF3, PIK3CA, Akt3, ITGB3, ITGA11, SPP1, NOS1, and ATP6V0B, were selected from Rap1, oxidative phosphorylation, and Alzheimer’s disease signaling pathways." (PMID 34359260, 2021). "In addition, overexpression of NMDAR2B in an inflammatory model of Alzheimer’s disease, which can be modulated by NOS (NOS1 belongs to this family) inhibitors." (PMID 32847502, 2020).
melanoma (29 papers, 2009 to 2026). A malignant, usually aggressive tumor composed of atypical, neoplastic melanocytes. "Our previous studies indicated that the transcriptional changes associated with NOS1 expression in melanoma were enriched in immune response pathways, particularly those related to IFN signaling." (PMID 41535256, 2026). "Further studies confirmed the association between NOS1 expression and drug resistance in other tumors such as melanoma where NOS1 overexpression led to a low response to interferon." (PMID 35740092, 2022). "The survival time of HDAC2-MUT mice was longer than that of HDAC2-WT mice, indicating that the HDAC2 mutation partially reversed the promotion of NOS1 on lung metastasis of melanoma." (PMID 31805977, 2019). "SNP genotypes of NOS1 are associated with an increased risk of melanoma." (PMID 41535256, 2026). "Analysis of the TCGA melanoma database showed that NOS1 expression is positively associated with several immune-related pathways, including the JAK-STAT, NF−κB, and TNF signaling pathways, suggesting a potential link between NOS1 activity and immune modulation." (PMID 41535256, 2026). "Co-immunoprecipitation experiments showed that Poly(I:C)-induced dimerization of IRF7 and IRF3 was reduced in NOS1 overexpressing melanoma cells." (PMID 41535256, 2026). "Considering that NOS1 is also expressed in tumor-infiltrating immune cells, we divided melanomas into high and low immune-infiltrating groups based on CD45 expression, stratified by the median CD45 expression level." (PMID 41535256, 2026). "NOS1 is expressed in 80% of melanomas, and NOS1 activity is higher in melanomas than in melanocytes." (PMID 41535256, 2026). "In NOS1-overexpressing melanoma cells, we observed a decrease in the level of IRF7 S-nitrosylation in both human IRF7-C481A A375 cells and mouse IRF7-C435A B16F10 cells." (PMID 41535256, 2026). "In melanoma, NOS1 expression increases with tumor progression and correlates with tumor immune escape through the inhibition of type I interferon (IFN) signaling." (PMID 41535256, 2026). "NOS1-selective small molecule inhibitors possess potent anti-melanoma activity in vivo and effectively inhibited the induction of PD-L1 stimulated by IFN-γ treatment." (PMID 41535256, 2026). "Our studies, along with others, have shown that NOS1 expression in melanoma induces dysfunction of type I IFNs signaling." (PMID 41535256, 2026). "Our study suggests that NOS1 expression in melanoma characterizes IFN-I signal disorders in response to innate immune stimulation through IRF7 s-nitrosylation." (PMID 41535256, 2026). "We utilized genetically modified NOS1 melanoma cells (either overexpressing or knocked out NOS1 in the mouse B16F10 melanoma cell line) to establish a lung metastasis model." (PMID 41535256, 2026). "We assessed the level of IRF7 S-nitrosylation and the impact of NOS1 expression on this modification in melanoma cells." (PMID 41535256, 2026). "Using melanoma transcriptional profiles from public databases, we evaluated the effect of NOS1 expression on the composition and function of immune cells in the tumor micro-environment and its impact on immunotherapy outcomes in tumor patients." (PMID 41535256, 2026). "The nuclear localization of IRF7 was also reduced in NOS1 overexpressing melanoma cells, which was partially reversed by high-dose Poly(I:C) treatment." (PMID 41535256, 2026). "Melanoma cells transform from melanocytes, which originally express NOS1 under ultraviolet light to promote cellular proliferation." (PMID 41535256, 2026). "We found some evidence of GxE interactions with sun exposure, notably, with MC1R, CAT and NOS1 genes in melanoma, HAL and IL23A in BCC and HAL and XRCC1 in SCC." (PMID 37537768, 2023). "Most notably, with MC1R, CAT and NOS1 genes in melanoma, HAL and IL23A genes in BCC and HAL and XRCC1 genes in SCC." (PMID 37537768, 2023).
melanoma (continued). "NOS1 secretion by melanoma cells is one mechanism that has been identified as contributing to dysregulated IFN signaling through in vitro analysis." (PMID 37741983, 2023). "The expression of NOS1 by cancer cells has been proven as having immune dysfunction effect by IFN signal dysfunction in circulating immune cells in patients with melanoma." (PMID 36864443, 2023). "NOS1 was identified as an inhibitory factor released by melanoma cells, which led to dysfunctional IFN-α p-STAT1 signaling in PBMCs." (PMID 37741983, 2023). "We further explored the clinical significance of NOS1 expression and its immune modulation from TCGA database of melanoma patients." (PMID 35538490, 2022). "To better understand the role of NOS1 expression on immune modulation and clinical significance in melanoma, we investigated a cohort of transcription data of melanoma under high dose of rIL2 treatment down load from GEO (GSE32611)." (PMID 35538490, 2022). "Here, we generated NOS1-knockout melanoma cells to explore the role of NOS1 on melanoma growth and interferon response, and provide possible mechanisms through global transcription analysis." (PMID 35538490, 2022). "In this study, we also observed that metabolic reprogramming is the major alteration in NOS1 deleted melanoma cells." (PMID 35538490, 2022). "The CRISPR/Cas9 system was used to generate NOS1-knockout melanoma cells and the biological characteristics of NOS1-knockout cells were evaluated by MTT assay, clonogenic assay, EdU assay, and flow cytometric assay." (PMID 35538490, 2022). "The results confirmed that NOS1 knockout inhibited melanoma growth of lung metastasis and increased the immune cell infiltration." (PMID 35538490, 2022). "NOS1 deletion suppressed the proliferation of melanoma A375 cells in culture, blocked cell cycling at the G0/G1 phase, and decreased the tumor growth in lung metastasis nodes in a B16 melanoma xenograft mouse model." (PMID 35538490, 2022). "The histopathology with hematoxylin and eosin (H&E) staining showed that nodules of NOS1-KO melanoma have less number of melanoma cells and display poor cell morphology compared with the WT group." (PMID 35538490, 2022). "Our data will prompt future research to target NOS1 or combined immunotherapy to control metastasis in melanoma patients." (PMID 31805977, 2019). "Meanwhile, it has been observed that NOS1 expression and increased NO production correlate with a poor prognosis in melanoma patients." (PMID 31805977, 2019). "To address this question, we investigated the regulation of NOS1 on the interferon response and clarified the relevant molecular mechanisms, which suggested a new means of targeting NOS1 in the treatment of melanoma." (PMID 31805977, 2019). "The expression of NOS1 in melanoma is closely correlated with dysfunctional type I IFN signaling and poor prognosis of patients." (PMID 31805977, 2019). "Overexpression of NOS1 in melanoma cells decreases IFNα-responsiveness and induces the S-nitrosylation of HDAC2-C262/C274." (PMID 31805977, 2019). "This study provides evidence that NOS1 induces dysfunctional IFN signaling to promote lung metastasis in melanoma, highlighting NOS1-induced S-nitrosylation of HDAC2 in the regulation of IFN signaling via histone modification." (PMID 31805977, 2019). "Increased NOS1 expression has been detected in melanoma, which correlated with dysfunctional IFN signaling and poor response to immunotherapy, but the specific mechanism has not been determined." (PMID 31805977, 2019). "Notably, in melanoma cells with NOS1 overexpression, the level of IRF7 induced by IFNα is similar to that observed in control cells, which suggests that the JAK/STAT1 pathway remains unaffected by NOS1." (PMID 41535256, 2026). "Understanding the specific role of melanoma NOS1 in immune regulation may provide insight into the cellular mechanisms behind the immune resistance during malignant progression." (PMID 41535256, 2026).
melanoma (continued). "Therefore, the down-regulation of tumor cell antigen presentation appears to be the most important tumor biological function of IRF7-C435A S-nitrosylation induced by NOS1 expression in melanoma cells." (PMID 41535256, 2026). "Targeting NOS1 signaling might be beneficial for overcoming immune therapeutically resistance, particularly in immune-cold melanoma phenotype." (PMID 41535256, 2026). "NOS1 promotes lung metastasis by inducing dysfunctional interferon signaling in melanoma." (PMID 41531533, 2025). "We next explored the effect of NOS1 deletion on the transcription profile of melanoma A375 cells." (PMID 35538490, 2022). "Our finding indicated that NOS1 plays a critical role in immune escape of melanoma." (PMID 35538490, 2022). "Thus, we generated a NOS1-knockout melanoma cell line NOS1-KO A375 (clone A5) for the following experiments." (PMID 35538490, 2022). "NOS1 signature predicts chemotherapy efficacy and the survival prognosis for melanoma patients." (PMID 35538490, 2022). "Thus, transcription data and cell experiments in vitro indicated that NOS1 expression plays a role in cell cycle regulation of melanoma cells." (PMID 35538490, 2022). "NOS1 expression predicts poor prognosis in patients with melanoma." (PMID 35538490, 2022). "Furthermore, our data analysis showed that 14% of the melanoma patients have genetic alteration on NOS1 gene, 8% on NOS2 and 18% on NOS3." (PMID 35326089, 2022). "Taken together, these results indicate that NOS1 may promote lung metastasis of melanoma by inhibiting IFN signaling." (PMID 31805977, 2019). "Moreover, expression of a mutant form of HDAC2, which cannot be nitrosylated, reverses the inhibition of ISG expression by NOS1 in vitro and decreases NOS1-induced lung metastasis and inhibition of tumor infiltrating lymphocytes in a melanoma mouse model." (PMID 31805977, 2019). "Our previous studies demonstrated that NOS1 was highly expressed in melanoma cells and involved in inhibiting the reactivity of PBMCs to IFNα, revealing the critical role of NOS1 in tumor immune escape, but the specific mechanism governing this role has not been determined." (PMID 31805977, 2019). "The effect of NOS1 on lung metastasis was assessed in melanoma mouse models." (PMID 31805977, 2019). "On the other hand, animal models indicate that NOS1 promotes lung metastasis of melanoma." (PMID 31805977, 2019). "The expressions of CD8A, GZMA, GZMK and PRF1 genes in the NOS1-high-expression group were significantly lower than those in the NOS1-low-expression group, indicating that NOS1 might play an immunoregulatory role only in “cold” melanoma." (PMID 41535256, 2026). "Thus, NOS1 expression may endow melanoma with cold tumor characteristics, leading to IFN treatment and resistance to immunotherapy." (PMID 41535256, 2026). "Therefore, NOS1 expression contributes to melanoma development by facilitating immune evasion." (PMID 41535256, 2026). "However, the immune inhibitory role modification by NOS1 expression might also contribute to the involve in its growth promotion in of melanoma." (PMID 35538490, 2022). "Targeting NOS1 might be benefit in melanoma therapeutic management." (PMID 35538490, 2022). "Our study showed that stable expression of NOS1 in melanoma cells induced dysfunction of IRF7 through S-nitrosylation, thereby completely impairing the type I IFN response of melanoma cells." (PMID 41535256, 2026). "To validate that C481A in humans and C435 in mice serve as the primary targets for NOS1-mediated nitrosylation, we deleted endogenous IRF7 in melanoma cells and reintroduced alanine-substituted versions (human IRF7-C481A or mouse IRF7-C435A)." (PMID 41535256, 2026). "Clinically, high expression of NOS1 correlated with poor survival prognosis and resistance to ICB anti-tumor therapies in melanoma cases with less immune cell infiltration." (PMID 41535256, 2026).